CD44 (CD44 molecule (IN blood group))
Diseases named in the same sentence as CD44 in open-access papers (continued):
Sharing a sentence is not in itself a finding about the gene and the disease.
tumor (continued). "Taken together, our analysis results indicated that CD44+ TAMs were not specific to EPNs and could be present in other but not all neurological tumors, which may be related to the diverse tumor microenvironments of different cancer types." (PMID 34824203, 2021). "Sorted CD44+ OSCC stem cells express high levels of stem cell markers, stemness and EMT-related genes, exhibit higher proliferation rate and secrete higher levels of inflammatory cytokines and angiogenic factors than a heterogeneous tumor cell population from OSCC tumors." (PMID 34205649, 2021). "With the addition of 10 μg/mL Met, the CD44 + CD62L + population of effector CD8+ T cells (CD8+ Teff) increased by 7.45% and the PD-1 expression was down-regulated, suggesting that Met might have potential anti-tumor activity." (PMID 34593005, 2021). "The xenograft tumour tissue in previous study were stained with the same antibodies, showing that Sox9, β-catenin increased, and β-catenin could be observed in more cytoplasm and nuclei of the xenografts formed by HCT116CD133+CD44+ shCldn7." (PMID 34281572, 2021). "Finally, we must not put aside the microenvironment where the tumor is developing, as there is evidence that under certain environment conditions, sCD44 competitively inhibits the binding of CD44 molecules to HA." (PMID 33505471, 2021). "Furthermore, TAMs also promoted tumor progression under hypoxia by interacting with corresponding receptors, such as EGFR- and FGFR2-promoting tumor cell proliferation, CD44-promoting tumor invasiveness, and VEGF-inducing angiogenesis to increase invasion ability of tumor cells." (PMID 34956900, 2021). "In the PDTX model, administration of SR3029 obviously delayed tumor growth, concomitant with an increased protein level of AES and a decreased expression of Wnt target genes (Axin2, Fibronectin and LEF1), stemness marker genes (CD44 and LGR5) and Notch target genes (HES1 and HES2)." (PMID 33754069, 2021). "According to the literature, CD44 can promote tumor metastasis through the regulation of ERK and AKT pathway, and our results indicate that over-expression of SRA1-L promotes the expression of p-AKT, CD44 and p-ERK, knockdown SRA1-L decreased the expression of p-AKT, CD44 and p-ERK." (PMID 34011971, 2021). "Once hyperthermia is applied on the thermosensitive liposomes, the tumor environment modulator MATT, a broad-spectrum synthetic enzyme inhibitor, and the prodrug will be rapidly released and HA–PTX will be quickly internalized in the cancer cells through CD44–HA affinity." (PMID 33981532, 2021). "However, CD44 and SOX2 are one of the key proteins that regulate tumor SCC stemness." (PMID 34421348, 2021). "Moreover, the levels of tumor metastasis-related molecules, HIF-1α expression, and LOX secretion were increased in RT-R-MDA-MB-231 tumor tissue compared to MDA-MB-231 tumor tissue and were even higher in CD24−/low/CD44+ tumor tissue." (PMID 34502547, 2021). "Based on regression analysis, CD44 marker was as independent predictor (p < 0.0001) for tumor grading and staging in CRC patients, suggesting that CD44 could be used as independent predictor of tumor development." (PMID 34837915, 2021). "The expression levels of CD44, CCND3, NCALD, MACF1 and KCTD15 were downregulated in the vast majority of LUAD histological subtypes compared with in normal samples; additionally, they were differentially expressed according to tumor stage and nodal metastasis status." (PMID 33281971, 2021). "Therefore, it can be speculated that CD44 and SAT1 may regulate immune checkpoints to involve in tumor immunity." (PMID 34249910, 2021). "Moreover, combined CD44-targeted NIR-PIT with programmed cell death protein 1 (PD-1) or CTLA4 checkpoint blockade was more effective in combination than as single therapies in syngeneic mouse models, including a minimally immunogenic tumor." (PMID 34064074, 2021).
tumor (continued). "Furthermore, macrophage-derived glycoprotein non-metastatic B facilitates the expansion of CSCs through CD44/IL-33 axis and promote metastasis in mouse tumor models." (PMID 35071018, 2021). "Single cells were separated into CD44+CD133+ and ΔCD44+CD133+ fractions using FACS, and purified CD44+CD133+ cells were then injected into secondary recipient NSG mice to verify whether these subpopulations were still capable of initiating tumor formation." (PMID 33994850, 2021). "Furthermore, we found that CD44 and ALDH1A1 were strongly expressed in tumor buds." (PMID 35083162, 2021). "However, the mechanisms of cooperativity between RHAMM and CD44 as well as the interaction of HA with these receptors in the processes of tumor cell migration and adhesion are not fully explained." (PMID 33981532, 2021). "Furthermore, the study suggested that CD44-negative CTCs undergo anoikis within 48–72 h after detachment from the tumor." (PMID 34209696, 2021). "In order to analyze whether this alteration affected the translational level, we explored these two promising candidates (CD44 and CDH1) and their potential clinical impact by evaluating a cohort of 100 patients with unique tumor location at the tongue followed-up by 10 years." (PMID 33976322, 2021). "However, the tumor volumes were significantly increased in RT-R-MDA-MB-231 cell-injected mice compared to MDA-MB-231 cell-injected mice, and CD24−/low/CD44+ cell-injected mice showed even greater enhancement of tumor growth than RT-R-MDA-MB-231 cell-injected mice." (PMID 34502547, 2021). "Interestingly, Cluster-6 shows expression for stemness markers CD117 and CD44, the tumor markers CD125, HE4 and EpCAM, and is negative for the immune and stromal markers, presenting as a potential cancer stem cell population." (PMID 33135052, 2021). "In addition to CD44, other CSC markers might be used to reflect the tumor heterogeneity and meanwhile to evaluate the peptide binding." (PMID 34789743, 2021). "Studies of mesenchymal cells or tumor cells have demonstrated that surface adhesion receptors, such as CD44, plays an important role of in the migratory cycle of T cells, while APE1 can cleave CD44 mRNA in vitro studies through exhibiting its endonucleases function." (PMID 33676448, 2021). "This contradiction could be attributed to the following reason: The fact that CD44 is upregulated in tumor tissues compared with non-tumor tissues may be indicative the role of CD44 in the occurrence of LUAD." (PMID 33372595, 2020). "The results showed that upregulation of circIFI30 could enhance the expressions of CD44, Twist and ZEB1 as well as decrease the expression of E-cad in xenograft tumor tissues, whereas knockdown of circIFI30 played an opposite role compared with the control group." (PMID 32497020, 2020). "For instance, HA-coated cationic liposomes containing cabazitaxel (a tumor cell inhibitor) and silibinin (a CSC inhibitor), displayed enhanced cytotoxicity with low IC50, hampered cell migration, and triggered apoptosis among human prostate tumor cells with CD44 expression." (PMID 33303029, 2020). "However, direct co-culturing of LS1034 cells with fibroblasts was much more effective in inducing tumor cell surface CD44 indicating that IL-6 is not the central in this scenario." (PMID 32685007, 2020). "Therefore, the different of soluble CSC markers, CD44, CD44v6, CD44v8-10 and EpCAM on patients with and without recurrence was analyzed according to tumor staging in order to avoid the effect of T, N and TNM stage on recurrence." (PMID 32039729, 2020). "Moreover, this tumorigenic population has been passaged several times and these cells were always able to induce tumors recapitulating the original tumor composition, forming both CD44+/CD24−/low tumorigenic and non-tumorigenic cells." (PMID 32257947, 2020).
tumor (continued). "Flow cytometry analysis of FVS− viable dormant tumor cell lines that regrew ex vivo had similar characteristics by the expression of neu antigen, the epithelial cell marker EpCAM, and a predominant CD24+CD44+ fraction over CD24-CD44+ cancer stem cell-like fraction." (PMID 33115528, 2020). "Moreover, activating EGFR in the head and neck CSCs enhanced expressing the genes engaged in the CSC rapid growth or proliferation (OCT4, BMI1, CD44, NANOG) and CSCs treatment through inhibiting EGFR declined the tumor growth and augmented the sensitivity to cisplatin." (PMID 32280305, 2020). "Moreover, the CD44-positive and PrPC-positive subpopulations of colorectal tumor cells have CSC properties, including tumorigenic and metastatic capacities, indicating that PrPC contributes to tumor maintenance by modulating CSC behaviors." (PMID 33276687, 2020). "Therefore, increased levels of CD44 in TMPs may explain the TMP-induced increased adhesive and invasive properties of tumor cells." (PMID 33050539, 2020). "Moreover, whether the selective pressure that chemotherapy had on the tumor cells along disease evolution is related to the distinctive pattern of expression of CD133 and CD44, deserves to be studied." (PMID 32188032, 2020). "In addition, the rate of CD44 positivity was significantly higher in tumor than in non-neoplastic tissues (p = 0.012)." (PMID 32850423, 2020). "However, no tumor growth was observed after implantation of CD44+/CD105+ cells and small tumors were present after implantation of CD44−/CD105+ cells (8.8 ± 0.9 mm3 after 7 weeks)." (PMID 32214151, 2020). "In addition, Ames and colleagues have reported that CSCs from various cell lines, as well as those isolated from primary tumor specimens based on the expression of several CSC markers including CD24, CD44, CD133, and ALDH, are eliminated preferentially by activated NK cells." (PMID 32391048, 2020). "Results showed that mean percentage population of cells expressing both Ep‐CAM and CD44 antigens were significantly higher in tumour and marginally significant in distal margin compared to normal tissues (0.83 ± 0.20, P = 0.0185), and (1.32 ± 0.32, P = 0.0050) vs (0.31 ± 0.06) respectively." (PMID 30950180, 2019). "Knockdown of CD44 expression in MDA-MB-468 cells did not affect tumor growth in vivo." (PMID 31762938, 2019). "Therefore, maintained L-selectin appears to have a role in the activation of tumor-specific T cells, as indicated by CD44 and CD27 expression at the site of the tumor, but not in tumor-draining LN or spleen." (PMID 31249570, 2019). "Treatment of LMP1/CD40-expressing lymphomatous mice with an anti-PD-L1 monoclonal antibody induced tumor regression with decreased spleen content, activation and proliferation rate of B-cells as well as a marked increase in T-cell activation, as assessed by CD62L and CD44 expression." (PMID 31382969, 2019). "Another known CSC marker, CD44 is enriched on CSC cells with CSC-like properties and may promote their function by forming a positive feedback loop with Ras signaling, and CD26+ colorectal CSCs contribute to tumor initiation by facilitating the EMT." (PMID 31137841, 2019). "Moreover, CD44 is a marker, together with CD24, of tumor-initiating cells or tumor stem cells." (PMID 31534630, 2019). "Interestingly, the enrichment of CD133 and CD44 positive cells were not evident in all cases of patients sample analysed, showing inter‐tumour heterogeneity among CRC patients." (PMID 30950180, 2019). "Since pathways such as Ras and PI3K/Akt are often dysregulated in tumor models, blocking CD44 alone may not be effective in inhibiting these amplified pro-tumorigenesis signals." (PMID 31762938, 2019). "Furthermore, the endogenous expression of CD44, N-casherin, Vimentin, Snail, and VEGF in tumor tissue from the U87 xenograft mice was suppressed by galangin treatment, indicating that galangin inhibited EMT and angiogenesis in the orthotopic xenograft mouse model." (PMID 31528214, 2019).
tumor (continued). "Moreover, tumors that formed by CD44+CD24−/lowLin− cells could be serially passaged and reproduced the cellular heterogeneity observed in the tumor of origin." (PMID 31619007, 2019). "Tumor cell expression of CD44 ranged from no expression to strong expression." (PMID 30999901, 2019). "CD44, CD133, CD24, CD117, Nestin, Nanog, and Oct3/4, as well as functional markers like ALDH1A1 and ABC transporters, have all been reported to be ovarian CSC markers, and indicators of chemoresistance, tumor-initiating potential, sphere-forming ability, invasiveness and poor prognosis." (PMID 31323899, 2019). "Note that, although the observed phototoxicity for cell viability of AvIR-PIT with Bio-CD44 was lower than that of AvIR-PIT with Bio-CD24, the anti-tumorigenic effect of the former was almost equal to the latter, suggesting superior effectiveness of CSC-targeting in PIT treatment on tumor control." (PMID 31787847, 2019). "In addition to pan-cytokeratin, we also attempted to detect SUM159 tumor cells in the bone marrow using CD44, which stained tumor cells in vitro, but did not detect any tumor cells in vivo (data not shown)." (PMID 30250146, 2018). "However, we did not detect the enrichment of CD44+CD24- cancer stem cells following ADR-induced tumor dormancy (data not shown)." (PMID 29774126, 2018). "In the primary cell culture of the tumor tissues obtained from the tumor periphery of four GBM patients, we obtained two SFCs (SFC-1 and SFC-2), both of which expressed much higher amounts of mRNA of neural stem cell markers CD133, Nestin, and CD44 than each PCs." (PMID 30210550, 2018). "However, treatment monitoring showed that the radiosensitiser AT13387 had no success in reducing the expression levels of CD44 in the treated tumour." (PMID 30149561, 2018). "Finally, using xenograft tumour models, we confirmed that IBC could reduce tumour growth in ER+ xenografts by inhibiting ERα and CD44 expression." (PMID 30179299, 2018). "Therefore, we propose that GFAP/CD90+/CD44+ EPN cells correlate with the expression of CD133, nestin, CXCR4 and SSEA-3, which could act as markers of enrichment for tumor-initiating cells." (PMID 29774098, 2018). "Since CD44 positivity represent stemness of a cancer cell line along with other markers such as OCT3/4, SOX2, KLF4, and Nanog, this approach may contribute to the retardation of tumor growth by restricting cancer stem cell population." (PMID 30619758, 2018). "CD44 expression was stronger in inflammatory and nonneoplastic cells than in tumor cells." (PMID 29682524, 2018). "In addition, CD90 and CD44 expression may explain the tumorigenic potential of these cells because CD44 and CD90 are also known as regulators of migration, invasion and tumor growth." (PMID 29774098, 2018). "Treatment of different tumor cells, DU145, LNCaP, and MCF-7 cells, with the demethylation agent 5-aza-CdR changed the histone code and methyl cytosine phosphate guanine (CpG)-binding domain protein (MBD) profile at the promoter regions of CD44, Cyclin D2, GLIPR1, and PTEN." (PMID 29747682, 2018). "CD44 knockdown in cancer diminished glutathione, but not HT in tumours." (PMID 29674746, 2018). "Additionally, IGF2BP1 prevents CD44 and PTEN mRNA turnover, consequently enhances CD44 expression, and induces the formation of invadopodia and therefore may promote tumor cell migration and invasiveness." (PMID 29954406, 2018). "Focusing on one of the most aggressive CTC type, which from the primitive tumor spreads to the CNS, we documented that CSF floating cancer cells overexpress syndecan-1, MUC-1 and, in a proportion of cases, the putative stem-cell markers CD15, CD24, CD44, and CD133 in BCLM." (PMID 28399903, 2017). "To investigate whether CSC could present different autophagy activation compared with tumor non-stem cells, we preliminarily confirmed that the co-expression of CD44 and CD117 is the most reliable marker for CSC identification in EOC." (PMID 28726781, 2017).
tumor (continued). "In addition, our western blot results showed that NLRP3, Caspase-1, IL-18 and IL-1β were highly expressed in the Tgfbr1/Pten 2cKO mice SCCHN tumor lysates compared with control wild type tongues, and the expression of BMI1, ALDH1 and CD44 were consistent with NLRP3 inflammasome." (PMID 28865486, 2017). "However, it is currently not known exactly how these CD44+/CD24- cells influence a whole tumor’s resistance to anti-cancer drugs." (PMID 28092266, 2017). "Overall, CD44 was less frequently expressed in tumor samples, being absent from malignant tumors." (PMID 28969033, 2017). "GSI reduces mammosphere-formation and tumor growth of CD44+/CD24+ cells, but not CD44+/CD24− cells." (PMID 28445439, 2017). "Also analyzed were non-tumor draining (brachial, BLN), tumor-draining lymph nodes (inguinal, ILN) and MC32A tumor microenvironment for changes in CD4+ FoxP3+ and proliferative/activated (i.e., Ki67+/CD44+) CD4+FoxP3- and CD8+ effector T cells." (PMID 29088720, 2017). "In transformed esophageal and oral keratinocytes, cells with low CD44 expression (CD44L) and epithelial properties are converted to CD44H cells with mesenchymal traits in response to transforming growth factor (TGF)-β30, 31, a potent EMT inducer present in the tumor microenvironment." (PMID 29170450, 2017). "GBM tumor cells expressed CD44 whereas the GBM stem cells tested had minimal to no CD44 expression." (PMID 28279210, 2017). "In vivo, however, no changes in total tumor CD44 were seen among treatment groups by IHC." (PMID 28778177, 2017). "Given that GD2, similar to previously reported CD44 and CD24 cell surface markers in other cancers, is able to separate cancer cells into two populations with differing tumor-initiating potential we hypothesize that GD2 would express CD44hiCD24lo cancer cell fraction." (PMID 29221154, 2017). "EpCAM and CD44 antibodies did bind distinctively throughout the FNAB tumor sample as seen through multiple z-axis images with 40 μm from the surface of the tumor (z/5), through the interior of the tumor (z/7 and z/9), with completion on the opposing side, 30μm from the surface (z/11)." (PMID 28085924, 2017). "In such a way, CD44/HA binding modifies the activity of different downstream signaling cascades, in particular, the MAP kinase and PI3/Akt pathways and consequently convey tumor cell proliferation, cell survival, cell motility and invasiveness and chemoresistance." (PMID 28403901, 2017). "Moreover, flow cytometry showed that the tumor tissue of EL4-Axl-bearing mice had higher percentages of activated CTLs (CD8+CD44+; MFI, 837) and NK cells (NK1.1+CD44+; MFI, 974) than in the mock controls (CD8+CD44+; MFI, 618, NK1.1+CD44+; MFI, 671)." (PMID 28423548, 2017). "By monitoring the changes in cellular phenotype using CD133/Olig2 and CD44 markers in the clinic, an improved therapeutic regimen could be designed to minimize acquisition of non-genetic tumor resistance." (PMID 28241049, 2017). "CD44 immunoreactivity decreases with the tumor advancement and may represent the negative PDAC prognostic factor." (PMID 28659655, 2017). "Flow cytometry assay indicated that XIAOPI formula had little influence on the distribution of CD44 and CD24, the cell surface markers for breast CSCs, indicating that the CSCs-inhibitory effects of XIAOPI formula might be attributed to the tumor microenvironment." (PMID 29109519, 2017). "Furthermore, an abundance of cell surface markers, such as CD133, CD44, CD26, CD24, CD166, have been reported to be useful in detection and identification of tumor cells, cancer initiating cells and CTCs, in breast, prostate, lung, colon, rectum, and other solid tumors." (PMID 27764803, 2016).